SDHB (succinate dehydrogenase complex iron sulfur subunit B)
Diseases named in the same sentence as SDHB in open-access papers (continued):
Sharing a sentence is not in itself a finding about the gene and the disease.
tumor (continued). "The R46X mutation in SDHB is unusual because it predicts loss-of-function, it targets a classical tumor-suppressor gene, and it occurs in PBMCs." (PMID 17487275, 2007). "NANETS guidelines highlight its benefit for tumor control, especially in SDHB-mutated cases." (PMID 41268153, 2025). "Subtype C1 exhibits a high frequency of mutations in genes associated with the pseudohypoxia pathway, such as VHL and SDHB, suggesting a unique adaptation to hypoxic conditions that may drive tumor progression." (PMID 41400463, 2025). "Research has shown that SDHB expression levels are strongly associated with tumor cell proliferation, migration, and invasion, particularly in the tumor microenvironment, where SDHB dysfunction may contribute to malignant transformation and tumor progression." (PMID 41333221, 2025). "While progress has been made with succinate dehydrogenase complex subunit B (SDHB)-deficient mouse and rat models, these models rely on radiation or genetic modifications to induce tumor development, which contrasts with the spontaneous tumor formation seen in human disease." (PMID 40576438, 2025). "False negative results, despite being less frequent, may be related to small and/or asymptomatic tumors and cluster 1 tumors (DA-producing PPGLs, biochemically silent PGLs of the head and neck region or SDHB mutated-neoplasms)." (PMID 38543140, 2024). "Furthermore, SDHB acts as a tumor suppressor and its inactivation is widely associated with cancer malignancy." (PMID 39584783, 2024). "Consequently, molecular evaluation of blood and tumor samples was performed, revealing an SDHB mutation." (PMID 39129823, 2024). "Thus, of the currently published human SDHB mutation carriers, around half are expected to develop tumours during their lifetime." (PMID 39000369, 2024). "Thus, germline mutation in SDHB combined with somatic LOH seem to be drivers that lead to the tumor's initiation and progression." (PMID 37175927, 2023). "Current evaluation of the tumor progression potential of PCC/PGL is based on multifactorial risk assessments, including the presence of SDHB mutation, larger tumor size, extra-adrenal location, dopamine hypersecretion, and several histopathologic scoring systems." (PMID 37008946, 2023). "Only one tumor was succinate Dehydrogenase B (SDHB)-deficient." (PMID 37545902, 2023). "In addition to the loss of SDHB expression, we also found that larger tumor size, extra-adrenal location, noradrenergic phenotype, and earlier age at diagnosis were significantly associated with shorter DFS in PCC/PGL, in agreement with previous findings." (PMID 37008946, 2023). "Immunohistochemical stain showing loss of SDHB expression and loss of heterozygosity (LOH) in the tumor tissue confirmed that the SDHB pathogenic variant found in this patient is the underlying cause of PA and likely the reason for the aggressiveness of macroprolactinoma and resistance to CBG." (PMID 38152133, 2023). "Notably, we identified a second pathogenic nonsense mutation in SDHB, which increased the risk of tumours." (PMID 37245000, 2023). "Additionally, SDHB deficiency switches energy metabolism from aerobic respiration to glycolysis, thus accelerating tumour cell proliferation or metastasis." (PMID 36717552, 2023). "According to Knudson’s two-hit model hypothesis, loss of heterozygosity (LOH) or copy number change, deep intronic change disrupting another SDHB allele, or epigenetic dysregulation in the tumor may have occurred during tumorigenesis in this patient." (PMID 35869040, 2022). "Indeed, along with extra-adrenal location, size of the tumour, and younger age, SDHB mutations are considered one of the risk factors leading to a malignant phenotype." (PMID 35884532, 2022). "However certain factors such as large tumor size, extra-adrenal location, increased dopamine secretion (> 3-fold increase), high Ki-67 index and presence of SDHB mutation (most important factor) to be associated with higher metastatic potential in PCCs." (PMID 36368995, 2022).
tumor (continued). "Furthermore, among such 15 synonymous mutation of SDHB gene, 9 tumor had RET gene mutation: exon 11, c.1901G > T, p.Cys634Phe (rs75996173): exon 11, c.2071G > A, p.Gly691Ser (rs1799939): or exon 11, c.1925 T > C, p.Val642Ala (rs766962871)." (PMID 35300626, 2022). "We selected the 5 tumours from the indolent cohort with the highest M2:M1 ratios and looked for other factors associated with aggressiveness; 3 of these also had the highest Ki67 scores, 3 had SDHB mutations and 4 out of the 5 were larger than 40 mm." (PMID 35975974, 2022). "SDHB-deficient tumor cells undergo a switch in cell metabolism, gaining oxidative phosphorylation and glycolysis capacity and then adapting to changes in the tumor microenvironment." (PMID 35743699, 2022). "In SDHD mutated tumours, the SDHB immunohistiochemistry may be misleading, as sometimes interpreted as immunopositive." (PMID 34834591, 2021). "To follow up the PPGL research, we will investigate whether adult heterozygous sdhb fish develop tumours in comparison to human SDHB mutations, which are at risk of developing PPGLs." (PMID 34680273, 2021). "In our cases, we observed complete loss of SDHB staining in mutated tumor cells." (PMID 34181326, 2021). "SDHB negativity was also associated with tumor cell necrosis (p = 0.007)." (PMID 33505538, 2021). "Oxidative stress has been recognized as a hallmark of cancers, which promotes tumor growth and malignant progression, especially for cancers with intrinsic altered metabolic signatures, such as SDHB-mutated PCPGs and isocitrate dehydrogenase 1 (IDH1)-mutated malignancies." (PMID 31979226, 2020). "Patients with germline SDHB gene mutations less commonly develop multiple tumours." (PMID 32252631, 2020). "In addition, low tumor levels of 5-hmC (resembling those in SDHB-deficient tumors) and positive 2SC staining have been detected in tumors with FH mutations, suggestive of altered DNA methylation and protein succination, respectively." (PMID 31362359, 2019). "Also, SDHD mutation has a distinctive phenotype and recognized increased age-related tumor risks with extremely destabilizing SDHB missense mutations." (PMID 31372201, 2019). "However, the tumour risks in SDHB mutation carriers are significantly less than originally thought and so there is (as in FH mutation carriers) a tension between over-investigation and early detection." (PMID 29680948, 2018). "Specific genotype-tumour risk associations provides a basis for novel investigative strategies into succinate dehydrogenase-related mechanisms of tumourigenesis and the development of personalised management for SDHB/SDHC/SDHD mutation carriers." (PMID 29386252, 2018). "Low SDHB expression was detected in the poorly differentiated cell lines of Mahlavu and SK-Hep1, whereas high expression was observed in the well-differentiated cell lines Hep3B and HepG2, indicating that down-regulation of SDHB expression was associated with tumor cell differentiation." (PMID 29449614, 2018). "Furthermore, the reduced SDHB expression was associated with advanced tumor stage and poor survival rate." (PMID 29449614, 2018). "The benefit of detecting asymptomatic, slow‐growing benign PGLs through presymptomatic screening of SDHB mutation carriers is uncertain, as intervention by either surgery or radiotherapy may cause more morbidity than the tumour itself." (PMID 29951630, 2018). "A recent study found that 25% of patients with asymptomatic SDHB mutations (identified through relationship to an index case) developed SDHB related tumours 2–6 years after identification of the mutation; the psychological impact of testing on asymptomatic carriers has not yet been assessed." (PMID 28965289, 2017). "Although RAPTAS might in some cases arise coincidentally, we note in two SDHB mutation-positive cases in our series (probands 9 and 18), age at tumor diagnosis was 60 years or older." (PMID 28973655, 2017).
tumor (continued). "Altogether, these observations suggest that these miRNAs may contribute to the maintenance of the undifferentiated state of SDHB-mutated tumours." (PMID 25625332, 2015). "More importantly, SDHB-loss cells displayed some tumor characteristics." (PMID 26294907, 2015). "Loss of heterozygosity could be detected in tumour DNA from 11/12 patients having somatic or germline mutations in the SDHB or VHL genes." (PMID 24466223, 2014). "Additionaly, we examined binding at the gene promoter of insulin-like growth factor binding protein 7 (IGFBP7), a tumour-related soluble factor whose transcript was highly upregulated in our microarray analysis of SDHB-deficient cells, and which has been shown to be under epigenetic control." (PMID 19849834, 2009). "Our data show that mitochondrial complex II mutations lead to upregulation of HIF1α targets in human tumor tissue and indicate an additional level of interplay between the SDHB and HIF1α proteins, i.e., a reciprocal effect of HIF1α in modulating components of the mitochondrial complex II." (PMID 16103922, 2005). "According to the literature, location of a primary tumor (adrenal vs. extra-adrenal), larger tumor diameter, older patient’s age at the time of diagnosis, biochemical tumor activity, presence of synchronous metastasis, and presence of germline mutations (SDHB) were adverse factors for OS." (PMID 40149362, 2025). "The absence or mutation of SDHB may be linked to the malignancy and prognosis of the tumor." (PMID 41333221, 2025). "In particular, somatic EPAS1 variants in SDHB-mutant tumours may have translational relevance." (PMID 38978571, 2024). "Although it is known that PPGL caused by pathogenic variants on SDHB are the most likely to progress into aggressive disease and these tumours have been associated with global hypermethylation, the impact of this methylation pattern as well as potential drivers of this behaviour remain unknown." (PMID 39622952, 2024). "focused their attention on exosomal DNA from Pheo/PGL exosomes, and they hypothesized that human serum exosomes may contain information regarding the presence of mutations of RET, VHL, HIF2α, and SDHB reflecting the mutation of their parental cells located in the tumour of origin." (PMID 37033265, 2023). "However, SDHB mutations alter metabolites, which may modulate the innate immune response and determine the pro-tumor immune response in vivo." (PMID 37840772, 2023). "Moreover, the recurrent tumor exhibited loss of heterozygosity (LOH) at the SDHB locus, that is according to Knudson's "two-hit" hypothesis of cancer causation." (PMID 34940133, 2021). "Furthermore, SDHB negativity was associated with tumor cell necrosis (p = 0.007)." (PMID 33505538, 2021). "Finally, COPPs were defined according to the following criteria: three clinicopathological parameters (tumor size > 7 cm, necrosis, and vascular invasion), loss of S-100 immunoreactivity (loss of intervening sustentacular cells), and loss of SDHB immunoreactivity (suggesting SDHB mutation)." (PMID 33193100, 2020). "Importantly, this data would suggest that the approach to clinical surveillance should be tailored to the SDHx subunit gene affected, as recent studies would suggest a higher risk of PPGL (and possibly of synchronous and multifocal tumours) with SDHB gene mutations." (PMID 30589099, 2019). "Furthermore, the hypermethylated phenotype of SDHB-related tumours apparently affects the promoter of the MGMT gene encoding the O6-methylguanine-DNA methyltransferase, the repression of which is a biomarker of a good response to alkylating agents such as temozolomide." (PMID 28471419, 2017). "Partial response or stable disease were observed in the patient with a VHL mutation and five of the six evaluable patients with an SDHB mutation, suggesting that patients with cluster 1 disease might be better responders to antiangiogenic treatments than patients with cluster 2 tumours." (PMID 28471419, 2017).
tumor (continued). "Moreover, an SDHB mutation has a poor genotype and phenotype correlation due to low penetrance and high variable expression, where even identical mutations give rise to different types of tumours in location, behaviour and severity." (PMID 29166454, 2017). "Notably, reduced SDHB expression in tumour tissues is associated with tumour de-differentiation." (PMID 25491408, 2014). "Immunohistochemistry results were as follows: CD117 (+), CD34 (+), Desmin (-), DOG-1 (+), Ki67 positivity in approximately 5% of tumor cells, S-100 (-), SDHB (+), SMA (few cells +), SOX-10 (-)." (PMID 40365338, 2025). "Immunohistochemical staining revealed diffuse KRT7, vimentin, PAX8, e-cadherin, SDHA, SDHB and fumarate hydratase expression in tumor cells." (PMID 39980061, 2025). "5hmC, TET1, TET2, and DNMT3B were primarily expressed in the nuclei of tumor cells, while SDHB exhibited granular cytoplasmic staining." (PMID 41290745, 2025). "Given its critical function in cellular metabolism and its established link to tumor development, SDHB is increasingly recognized as both a significant prognostic biomarker and a promising therapeutic target." (PMID 40724918, 2025). "Germline testing is recommended for SDHA, SDHB, SDHC, and SDHD across all ages and tumor types in the setting of SDH‐deficient staining and/or when an SDHx PV is identified in the tumor." (PMID 39927693, 2025). "This contrasts sharply with tumours like adrenocortical carcinoma, and renal papillary carcinoma, where high SDHA and SDHB expression associated with improved survival." (PMID 41350470, 2025). "In the multivariate Cox regression analysis, combining all histopathological and immunohistochemical features, SDHB loss, mitoses > 3/10 HPF, and larger tumor size (> 5.1 cm) were found to be associated with lower metastasis-free survival in PCC/PGL patients." (PMID 40445576, 2025). "Summary of existing guidelines for recommendations of SDHB immunohistochemistry (IHC) and molecular tumor analysis, and timing in relation to KIT/PDGFRA testing." (PMID 39927693, 2025). "Histopathological features associated with distant metastases (including BM) are abdominal location (66.7%), tumor size >5.1 cm, >3 mitoses/10 HPF, SDHB loss, vascular and capsular invasion, nuclear pleomorphism, and confluent necrosis." (PMID 41268153, 2025). "Immunohistochemical profiling showed CD117 (+), CD34 (+), Desmin (-), DOG-1 (+), Ki67 (approximately 5% positive tumor cells), S-100 (-), SDHB (+), SMA (a few cells +), and SOX-10 (-)." (PMID 40365338, 2025). "Assessing these differences for each individual gene in association with tumor location shows that proportionally more HNPs were reported for European patients with PVs in SDHA, SDHB, SDHC, and SDHD than for Asian patients." (PMID 38481600, 2024). "An untargeted metabolomic approach uncovered an overactive polyamine pathway in the SDHB_KD cells that was subsequently fully validated in a large set of human SDHB-mutant PPGL tumor samples." (PMID 39337514, 2024). "Here we report a case of SDHB-mutated metastatic PGL, wherein the patient showed significant tumor shrinkage and complete symptom remission following chemotherapy." (PMID 39744181, 2024). "Allografted mice models using SDHB-silenced cell lines showed tumour growth and developed metastases." (PMID 39000369, 2024). "Correlation of plasma SFR with tumor volume supports a previous study, in which serum succinate was shown to function as a biomarker for tumor recurrence and tumor burden in 3 patients with metastatic SDHB-related PPGL." (PMID 39145115, 2024). "Tumour SDHB expression as determined by immunohistochemistry largely corresponded with the literature on patients with hereditary disease." (PMID 37434651, 2023). "This study aimed to clarify the potential effect of SDHB IHC as a predictive marker for tumor progression in PCC/PGL patients." (PMID 37008946, 2023).
tumor (continued). "P/LP variants identified in tumor-only sequencing of GISTs were almost exclusively germline in certain genes, such as BRCA1, BRCA2 (4/4 variants), and SDHB (10/11 variants)." (PMID 36593350, 2023). "The post-operative pathologicalimmunohistology showed the tumor to be a Ki-67 < 1%, SDHB+, SMA+, CD34+, CD117+, DOG-1+,and Desmin+ GIST with tumor regression grade 2 and negative margins." (PMID 36632625, 2023). "SDHB follows an autosomal dominant pattern of inheritance and 18–40% of patients will develop a tumor, most often diagnosed around 30 years of age." (PMID 37024931, 2023). "With the recognition of elevated succinate causing aberrant activation of CDK5, the anti-CDK5 inhibitor MRT3-007 was shown to suppress tumor growth in vitro as well as in xenograft mouse models with SDHB knockout." (PMID 36897220, 2023). "Accordingly, SDHB protein expression was also increased in SNORA14A-overexpressing tumour xenografts compared to control xenografts." (PMID 36717552, 2023). "To further elicit better predictors amongst the range of PD-L1 expression in tumor tissues, we grouped the samples based on three genetic backgrounds: sporadic cases, pseudohypoxia cluster (SDHB, VHL, EGLN1, EPAS1) and kinase signaling cluster (RET, NF1)." (PMID 36439433, 2022). "SDHB IHC is a cheap, reliable, readily available and quick test to screen tumours with vacuolar changes." (PMID 35938916, 2022). "Surprisingly, SDHB tumor cells (originating from various anatomical locations) were less heterogeneous than their RET counterparts (originating from the adrenal gland)." (PMID 36046044, 2022). "Under HE staining, it was composed of tumor cells of uniform size with abundant cytoplasm arranged in nests, with IHC CgA (+), Syn (+), SDHB(-), and Ki-67 2%." (PMID 36387130, 2022). "Of the 35 tumours analysed for genetic variants, 25 carried variants in SDHD, 7 in SDHB and 1 in SDHC." (PMID 36178902, 2022). "Hierarchical clustering of metaprogram-scored cells revealed two major clusters separating RET from SDHB tumor cells." (PMID 36046044, 2022). "To assess the inter-tumoral heterogeneity between RET and SDHB PCPG tumor cells, we selected and re-clustered tumor cells." (PMID 36046044, 2022). "Specifically with the SDHB-associated PPGLs, in addition to higher Ki67 scores and lower cytotoxic T-cell proportion, there was also a higher infiltration of macrophages, with M2 macrophages dominating in aggressive SDHB tumours compared to indolent ones." (PMID 35975974, 2022). "For instance, the presence of SDHB mutations, ATRX mutations, and telomerase inactivation have been correlated with the neoplasm’s metastatic potential or multifocal primary disease." (PMID 36010170, 2022). "SDHB tumours are known to have a greater metastatic potential and the lower levels observed in these tumours correlate with this behaviour." (PMID 35975974, 2022). "There were significantly higher levels of CD4 Th lymphocytes in VHL tumours compared to SDHB tumours and the lowest levels of both Th and Tc lymphocytes were observed in PPGLs with underlying SDHB mutations." (PMID 35975974, 2022). "SDHB immunohistochemistry is a well-validated tool for detecting SDH-related neoplasia after surgery." (PMID 35892689, 2022). "Analysis showed an SDHB (c.565T>G, p.C189G) and PTEN (c.834C>G, p.F278L) missense mutation in tumor DNA." (PMID 35498434, 2022). "HLRCC-specific probes were selected that had β-values >0.5 in at least 13 out of the 15 HLRCC tumors and <0.2 in all other tumor and normal samples, including SDHB-RCC tumors, and this identified exactly 25 CpG island probes." (PMID 36455002, 2022). "In summary, NMF analysis revealed two main transcriptional programs in PCPG that separate RET from SDHB tumor cells." (PMID 36046044, 2022). "The M9 ‘hormone synthesis’ program was more enriched among the SDHB tumor cells, mainly due to patient P313." (PMID 36046044, 2022).